PGR (progesterone receptor)
Diseases named in the same sentence as PGR in open-access papers (continued):
Sharing a sentence is not in itself a finding about the gene and the disease.
tumor (continued). "Studies investigating mortality adjusted for age, mutation status, tumour size, nodal status, oestrogen receptor status, progesterone receptor status, HER2 receptor status, BC treatment (chemotherapy /surgery /tamoxifen) and centre." (PMID 36900415, 2023). "We tested the sample size using all the cases for association analyses, but only the Progesterone Receptor (RP) expression and tumor number (multifocal or single nodule) presented significant p values." (PMID 36681070, 2023). "A significant correlation was found between the risk of distant metastasis and tumor size, and the expression of PgR and HER2." (PMID 36612033, 2022). "The nomogram identified 8 clinicopathological variables that were associated with SLN positivity: age, tumor size, tumor type, tumor location, lymphovascular invasion, multifocality, estrogen receptor status and progesterone receptor status." (PMID 35794594, 2022). "EIF4A1 snoRT levels in tumor specimens also proved to be strongly associated to patients’ specific survival, mirroring the ER and PGR status." (PMID 35996163, 2022). "WTAP expression was positively associated with tumor size and grade, and negatively associated with axillary lymph node metastasis, estrogen and progesterone receptor status." (PMID 35046505, 2022). "No other clinical-pathological baseline pre-treatment variable such as tumour stage, nodal stage, oestrogen receptor, progesterone receptor expression, and Ki67 expression was found associated with pCR." (PMID 36374768, 2022). "Cox regression analysis found that histopathological type, tumor size, lymph node status, progesterone receptor (PR) status, Ki-67, and NRI were independently associated with OS." (PMID 36145159, 2022). "In summary, we identified significant differences in the expression levels of ESR1, ESR2, and PGR mRNAs in different cancer types, which associated with tumor progression and clinical prognosis." (PMID 34322374, 2021). "In a study of 633 breast cancer patients, ST6GAL1 expression was associated with tumor stage, survival and estrogen receptor (ER)/progesterone receptor (PR)/human epidermal growth factor receptor 2 (HER2) status." (PMID 33921986, 2021). "Taken together, it appears that the plasma S1P levels were associated with tumor progression, in addition to the PgR status." (PMID 34948163, 2021). "It was concluded that there is a correlation between miR-3117 rs7512692 variant and tumor grade (p=0.031); also, a correlation between miR-1269 rs73239138 variant and progesterone receptor status (p=0.006)." (PMID 33507700, 2021). "In patients with UTEA, the expression levels of both ERa and PGR proteins were conversely associated with tumor grade and stage." (PMID 34322374, 2021). "The loss of ERα and/or PgR in relapsing tumors or after primary systemic treatment probably indicates the selection of HR-negative cells in a heterogeneous pool of tumor cells." (PMID 34638241, 2021). "The expression of ERa protein was positively correlated with a high tumor stage, whereas the expression of PGR protein was conversely associated with a high tumor stage in patients with OV." (PMID 34322374, 2021). "TNBC is the most aggressive subtype, associated with higher metastasis rate and tumor grade and lacks the expression of estrogen receptor (ER), progesterone receptor (PR) and HER2, ruling out endocrine and trastuzumab therapies as treatment options." (PMID 34344433, 2021). "For RFS, the ER, PgR status, lymph node number, tumor grade, tumor size and risk score were significantly associated with RFS (all p < 0.05)." (PMID 35154262, 2021). "Taken together, the expression of ESR1 and PGR was significantly associated with pan-cancer tumor stage." (PMID 34322374, 2021). "In BC, γH2AX is associated with lower estrogen receptor (ER) and progesterone receptor (PR) expression and poor clinicopathological characteristics, including larger tumor size, higher grade, and more lymph nodes infiltration." (PMID 34595180, 2021).
tumor (continued). "ESR1, ESR2, and PGR mRNAs were found to be differentially expressed in different cancer types, and were associated with tumor progression and clinical prognosis." (PMID 34322374, 2021). "The increased levels of fractalkine were associated with the estrogen/progesterone receptor status of the tumour." (PMID 32321535, 2020). "These include the aryl hydrocarbon receptor (AHR), the progesterone receptor (PR), and, with particular relevance to macrophage‐rich tumor microenvironments, tumor‐associated macrophages (TAMs)." (PMID 32918364, 2020). "Regarding OS, CV was associated with significantly lower risk of death independently of other relevant clinical or tumor-related variables, with the survival advantage being limited to patients with HR+ BC, and in particular to patients with ER+ PgR+ disease." (PMID 32155941, 2020). "NeoGATA3 mutations were significantly associated with lower tumor stage, grade, and size and with expression of progesterone receptor (PR), all factors predicting better outcome." (PMID 32587399, 2020). "Meanwhile, we were not given the strong hint with the association between expression of PD-L1 and age (P = .051), tumor size (P = .466), histologic grade (P = .779) as well as progesterone receptor status (P = .167)." (PMID 33285715, 2020). "METTL14 expression was negatively associated with tumor grade and positively associated with patient age, estrogen, and progesterone receptor status." (PMID 33134390, 2020). "EC is a hormone dependent disease where the expression of estrogen receptor (ER) and progesterone receptor (PgR) has been associated with histological tumor differentiation, response to therapy and metastatic potential." (PMID 32679719, 2020). "Hsa_circ_0008673 expression was associated with larger tumor size, distant metastasis, positive estrogen receptor (ER) status, and positive progesterone receptor (PR) status." (PMID 32808350, 2020). "The HER2 rs1058808 (GG vs GC vs CC) SNP was associated with both progesterone receptor status (P = 0.01) and tumor size (P = 0.013)." (PMID 31888550, 2019). "IL-32θ expression was associated with tumor status, estrogen receptor (ER), progesterone receptor (PR), human epidermal growth factor receptor 2 (HER-2) status, and molecular classification characteristics." (PMID 31126309, 2019). "Functional analysis confirmed that 39 genes were associated with the processes of tumour formation and cancer progression of which two (PGR and ESR1) were common to four cancers of women." (PMID 31879572, 2019). "A previous study of breast cancer defined a 112-gene CSF1 response signature associated with higher tumor grade, decreased expression of estrogen receptor (ER) and progesterone receptor (PR), and higher mutation rate." (PMID 30930117, 2019). "Because hormone replacement therapy reduces CRC risk, progesterone receptor likely functions as a tumour suppressor." (PMID 31200767, 2019). "In terms of tumor biology, there was an association between low Cx43 and ER, PgR, and HER2 negativity and triple negative tumors (all p < 0.0001)." (PMID 30474779, 2019). "SLC7A5 expression is associated with increased tumor size, high nuclear grade, high Ki-67 labeling index, ER negativity, and progesterone receptor (PR) negativity in breast cancer." (PMID 29562706, 2018). "Breast conserving surgery, lower tumor size, number of positive lymph nodes and positive ER/PgR status were associated with improved outcome in terms of both DFS and OS." (PMID 30063723, 2018). "Nuclear and cytoplasmic BAG-1 expression was associated with low-grade tumours, ER and PgR positivity, and improved overall survival but was negatively correlated with HER2 and the triple-negative phenotype." (PMID 28510570, 2017). "Their clinical outcome was retrospectively reviewed and tumour samples collected from diagnostic core biopsies were analysed for progesterone receptor (PgR), HER2 and Ki67 using immunohistochemistry." (PMID 29284000, 2017).
tumor (continued). "Among baseline tumor characteristics determined at initial biopsy, progesterone receptor expression was associated with EFS, with higher risk of relapse in patients with PR- tumors (HR = 3.25, log-rank P < 0.01)." (PMID 28057031, 2017). "Tumor expression of the estrogen receptor (ER) or progesterone receptor (PR) has been shown to be positively associated with the prognosis of gynaecolgical cancers including endometrial cancer and breast cancer." (PMID 29137401, 2017). "The following factors can be used to separate patients with lower and higher risk of relapse and death: Nodal status, primary tumor size, ER/PgR level, histologic tumor grade, proliferation fraction (Ki67), lymphovascular invasion." (PMID 28407750, 2017). "Nevertheless, no statistical significant association was detected in a model including ER and PgR status together with age, tumour size and lymph node status (HR: 1.38; 95%CI: 0.91–2.1; p = 0.12)." (PMID 28345661, 2017). "On the other hand, the expression of most genes was associated with clinicopathological factors including tumor grade, tumor size, ER and progesterone receptor (PR) status, and PAM50 subtype." (PMID 29228969, 2017). "Overall, higher tumor grades were associated with decreased estrogen receptor expression and increased progesterone receptor expression." (PMID 27626480, 2016). "Multivariate analysis (Cox proportional hazards model) was also used to assess the influence of COX-2 mRNA level on MFS, together with histological grade, lymph-node status, tumor size, estrogen and progesterone receptor status and PIK3CA mutations." (PMID 27835884, 2016). "High expression of calpastatin was associated with ER positive tumours (χ2=5.720, d.f.=1, P=0.017) and high calpain-1 expression was associated with PgR positive tumours (χ2=5.457, d.f.=1, P=0.019)." (PMID 27323818, 2016). "We have shown that IHC determined PgR positivity in at least 10 % of the tumor cells predicts reduced recurrence risk after adjuvant tamoxifen therapy for patients with ER-positive tumors." (PMID 27722840, 2016). "Further, the association of ADC with tumor volume, stage, hormonal receptors [estrogen receptor (ER), progesterone receptor (PR), and human epidermal growth factor (HER2)], and menopausal status was investigated." (PMID 27242965, 2016). "There have been some discrepancies in the reported rate of gain or loss of ERα and PgR expression in metastases relative to the primary tumour." (PMID 27189371, 2016). "The tumor sample harbouring a PIK3CA mutation that was ER-negative was progesterone receptor (PgR)-positive." (PMID 26630576, 2015). "In univariate analyses, high tumor cell density (p = 0.006) and high tumor stromal cell density level (p = 0.045) of progesterone receptor were both significantly associated with tumor progression and clinical failure." (PMID 25723513, 2015). "Expression of the two receptors was associated (Spearman's ρ=0.555, P=0.000), and expression of progesterone receptor was higher in tumours that express oestrogen receptor than it was in those that do not (Mann–Whitney U test, P=0.000)." (PMID 25900183, 2015). "Previous reports have shown that substantial progesterone receptor (PgR) positivity in tumours is commonly associated with a better prognosis." (PMID 25938238, 2015). "High p-mTOR and positive p-ERK1/2 staining were both associated with a positive PgR status and low tumor grade." (PMID 24447434, 2014). "Established clinical, pathologic features and biomarkers such as patient age, tumor size, nodal status, tumor grade, ER, progesterone receptor (PR), and HER2 status are used to estimate a patient’s risk for recurrence and to guide treatment options." (PMID 24676558, 2014). "Analyzed by Freedmans%, age, tumour size, lymph nodes, grade, diagnostic period, ER and PgR explained 55.5% of the observed differences in mortality between non-symptomatic and symptomatic cases." (PMID 24678853, 2014).
tumor (continued). "In contrast, the methylation of heparanase had no apparent associations with the following prognostic factors: tumor size (p = 0.078), node metastasis (p = 0.133), ER positivity (p = 0.101), PgR positivity (p = 0.528), and HER2 expression (p = 0.196)." (PMID 24632672, 2014). "In PJS-associated SCTAT, the serum tumor marker inhibin and immunohistochemical markers inhibin, estrogen receptor, progesterone receptor, and androgen receptor have been studied as diagnostic tools, though morphology is the gold standard." (PMID 25530972, 2014). "Genetic association of rs148972953 with tumour characteristics (oestrogen and progesterone receptor status and metastases)." (PMID 23341997, 2013). "Univariate analysis indicated that in general T, pN, LNR, as well as tumor expression of the estrogen receptor, progesterone receptor, and HER2 were associated with overall, disease-free, and distant metastasis-free survival (all P-values <0.05)." (PMID 23626682, 2013). "The study also revealed that HER2 status changing from negative to positive was associated with a certain decrease in ER and PgR expression between primary tumor and liver biopsy." (PMID 23424693, 2013). "NGAL expression in breast carcinoma cells was significantly associated with histological tumor type, hormone receptor (HR) status, estrogen receptor (ER) and progesterone receptor (PR) status." (PMID 23056218, 2012). "In primary tumors, UCHL1 methylation was associated with clinical stage and progesterone receptor status, indicating its potential as tumor marker for this cancer." (PMID 22279545, 2012). "The risk allele of rs3803662 has been shown to associate with ER and PgR status, grade of tumours and diagnosis before the age of 60." (PMID 23270421, 2012). "A case–control study was conducted in China, 2004–2005 to examine the association by menopausal status, oestrogen (ER) and progesterone receptor (PR) status of the tumour." (PMID 21829196, 2011). "On subgroup analysis, only ER-positive/progesterone receptor (PgR)-positive tumours were associated with improved survival (P=0.004)." (PMID 19018258, 2008). "We examined the lymphocytes in the vicinity of or inside the tumour, in an attempt to associate their presence/absence with Her-2, ER, or PgR expression." (PMID 17892570, 2007). "Clinical correlation in our study showed that YKL-40 antigen detection was associated with larger tumor size, poorer tumor differentiation, and a higher likelihood of estrogen and progesterone receptor negativity." (PMID 17286869, 2007). "Baseline levels of ERα-p-Ser118 have been positively associated with favourable tumour characteristics, with a better outcome after therapy with tamoxifen and with expression of PgR." (PMID 17712311, 2007). "An association between the tumour margin status and Her-2, ER, or PgR expression has been investigated in several studies." (PMID 17892570, 2007). "Further, we evaluated if associations differed by oestrogen and/or progesterone receptor tumour status." (PMID 17940510, 2007). "Significant associations were also observed with tumor ER and progesterone receptor (PR) status, the presence of LN disease, and primary tumor grade." (PMID 18081427, 2007). "Higher Ki-67 proliferation indices were associated with PgR− tumours (median 28.3%, PgR+ 22.9%; P=0.042)." (PMID 15611798, 2005). "Higher Ki-67 proliferation indices were associated with PgR− tumours (PgR− median 28.3%, PgR+ 22.9%; P=0.04)." (PMID 15611798, 2005). "A direct association between VEGF and tumour size (P=0.001) as well as between PgR and bcl-2 (P=0.001) were present only in IDC." (PMID 12402149, 2002). "VEGF levels were found to be positively associated with tumour size and negatively associated with ER and PgR status." (PMID 12232762, 2002).
tumor (continued). "Since there is no significant variation in tumor biomarkers (i.e., estrogen or progesterone receptor positivity), the underlying cancer biology could be reinforced to be similar to menopausal status with little hormonal impact on the tumor traits." (PMID 40573326, 2025). "Univariate analysis demonstrated that tumor size stage, lymph node status, estrogen receptor status, progesterone receptor status, and molecular subtype were associated with RFS (all p < 0.05), and were included as CP features to construct the DeepTEPP scoring network." (PMID 38329503, 2024). "We found that PGR expression was increased in mouse PanIN cells and PDAC cells compared with adjacent normal cells, suggesting that elevated PGR expression may be associated with PDAC tumor initiation." (PMID 38424455, 2024). "The SAE1 overexpression was significantly associated with the tumor size, tumor-node-metastasis stage, estrogen receptor, progesterone receptor, human epidermal growth factor receptor 2, and whether or not it was a triple-negative BC." (PMID 39742381, 2024). "Moreover, the promising results of utilizing selective progesterone receptor modulators (SPRM) in controlling UF-associated symptoms such as bleeding as well as tumor shrinkage, further supports the role progesterone plays in UF pathogenesis." (PMID 37190026, 2023). "We found that DNAm AA was positively associated with ESR1 and PGR gene expression in both tumor and normal tissue samples, suggesting that the activation of estrogen signaling pathway may accelerate breast tissue aging." (PMID 36991516, 2023). "Variables associated with low pathologic complete response rates were tumor grades 1-2 (OR = 0.55; 95% CI = 0.37-0.81; p = 0.03), estrogen receptor positivity (OR = 0.65; 95%; CI = 0.43-0.97; p=0.04), and progesterone receptor positivity (OR = 0.44; 95% CI = 0.29-0.65; p = 0.0001)." (PMID 37871573, 2023). "Additionally, the effects of amcenestrant on ER degradation, through the assessment of tumor biomarker (Ki67, B cell lymphoma 2 [Bcl-2], and PgR) expression, and ESR1 mutation profiles were investigated." (PMID 36977973, 2023). "To verify whether four EMT-related genes (SIX1, SIRT2, CDKN2A and PGR) are associated with tumor metastasis, we performed transwell migration assays, transwell invasion assays and wound healing assays to investigate their relationship." (PMID 37723477, 2023). "High ezrin expression was significantly associated with adverse survival of patients whose tumours were categorised as receptor (oestrogen receptor (ER), progesterone receptor (PgR) or HER2) positive (p < 0.001) in comparison to those categorised as triple‐negative breast cancer (p = 0.889)." (PMID 36938826, 2023). "However, PgR status and tumour grade were significantly associated with ∆Ki672week and remained significant in multivariable analysis." (PMID 37046348, 2023). "Parameters that could be taken into account are primary tumor size, axillary nodes, patient’s age, estrogen and progesterone receptor status, genomic risk of recurrence, and intrinsic subtype, the latter two when available." (PMID 36362392, 2022). "Here, we systematically analyzed estrogen receptor α (ERα) and progesterone receptor (PR) expression by immunohistochemistry in a well-characterized series of patients with CP (n = 41) and analyzed their potential association with tumor aggressiveness features." (PMID 35012020, 2022). "A recent GWAS identified several novel loci that were associated with at least one tumour feature (ER-status, progesterone receptor status, tumour grade, human epidermal growth factor 2 receptor) and also loci that differed by the molecular subtype, luminal or non-luminal, of breast cancer." (PMID 34285278, 2021).